CCND1 (cyclin D1)
Diseases named in the same sentence as CCND1 in open-access papers (continued):
Sharing a sentence is not in itself a finding about the gene and the disease.
hepatocellular carcinoma (continued). "For instance, hepatocellular carcinoma (HCC) frequently exhibits 2 to 10 fold amplification of oncogenes such as Cyclin D1, CDKN1A, KRAS, and MDM2." (PMID 41515655, 2026). "Previous research has shown that MCM7 promotes hepatocellular carcinoma (HCC) progression via the MCM7-cyclin D1 signaling pathway, suggesting its potential as a target for therapeutic intervention in hepatocellular carcinoma." (PMID 40789837, 2025). "In human hepatocellular carcinoma SMMC-7721 cells, in addition to low β-catenin both in the cytoplasm and nucleus by promoting its phosphorylation (Ser33/37/Thr41), the compound also caused target genes c-Myc and cyclin D1 to decrease, reducing a wide range of cancer properties." (PMID 40427472, 2025). "An overall study based on a gene regulatory network in human hepatocellular carcinoma (HCC) revealed that abnormal regulation of the microRNA-19a/cyclin D1 axis has carcinogenic potential and poor prognosis." (PMID 35290415, 2022). "Similarly, CCND1 over-expression has been reported in the carcinoma of the liver and CCND1 autophagy-dependent degradation leads to RB-driven inhibition of cell proliferation and tumor progression and subsequent suppression of the E2F transcriptional activity necessary for entering S phase." (PMID 34445095, 2021). "In human and murine models of hepatocellular carcinomas (HCC), induction of autophagy led to CCND1 ubiquitination and its recruitment into autophagosomes via SQSTM1, formation of autophago-lysosomes, and degradation with suppression of tumor growth." (PMID 34445095, 2021). "Interestingly, we noticed that knockdown of ZFX suppressed the expression of several important β‐catenin target genes such as c‐Myc, c‐Jun, and cyclin D1 in hepatoma cells, whereas enforced expression of ZFX upregulated these downstream effectors both in mRNA and protein levels." (PMID 28156061, 2017). "Here, we investigated the functional role of the cyclin D1-dependent activation of Smad2/3 and Smad4 in hepatocellular carcinoma (HCC) CSCs and in HCC primary tumors." (PMID 28415588, 2017). "Thus M2 macrophages in the hepatocellular carcinoma microenvironment generate large amounts of interleukin-17, which suppress oxaliplatin-induced tumor cell apoptosis by activating chaperone-mediated autophagy and in turn reducing cyclin D1 expression." (PMID 28591705, 2017). "It is interesting to examine whether the inhibitory action of berberine on Cyclin D1 expression in liver cancer cells shares the same mechanism and to figure out the exact machinery that undergoes Cyclin D1 suppression in human hepatoma cells exposed to berberine." (PMID 27854312, 2016). "Herein, the tumor relevance of G870A polymorphism, the association between cyclin D1 variant expression and G870A genotype, and the oncogenic potential of cyclin D1 variants in HBV-related hepatocellular carcinoma (HCC) were examined." (PMID 25851350, 2015). "CHEK1, CDC25A, and CCNE1, together with CCND1, CCND3, CDK4, CDK6, BTRC, E2F3, and FOXK1, were previously identified as the targets of miR‐497∼195 cluster in hepatocellular carcinoma." (PMID 40548926, 2025). "Canagliflozin-treated HepG2 cells demonstrated increased expression of the cell growth regulator hepatocyte nuclear factor 4 (HNF4), with a reduced expression of cyclin D1, cyclin D2, and cdk4, resulting in cell cycle arrest in a hepatocellular carcinoma (HCC) cell line." (PMID 40869400, 2025). "These included that SHCBP1 knockdown prevented the cell proliferation of hepatocellular carcinoma (HCC) and induced G0/G1 arrest by downregulating p-ERK1/2 and cyclin D1 expression, emphasizing its involvement in MEK/ERK signaling." (PMID 40657397, 2025).
hepatocellular carcinoma (continued). "By binding with cell cycle regulatory element cyclin D1, E2F8 promotes hepatocellular carcinoma cell proliferation." (PMID 39999286, 2025). "As a result, STAT3-regulated genes Bcl-2, cyclin D1, Bcl-xL, survivin, Mcl-1, and VEGF were downregulated, inhibiting proliferation and prompting substantial death in hepatocellular carcinoma cells." (PMID 38310190, 2024). "Regarding the mechanisms involved, in vitro studies suggest that the overexpression of NR0B2 can inhibit hepatocellular carcinoma (HCC) lesions’ formation and tumor growth, potentially through SHP’s (the protein corresponding to NR0B2) regulation of cyclin D1." (PMID 39336801, 2024). "In hepatocellular carcinoma (HCC) xenografts, B029-2 efficiently inhibited the HAT activity of p300/CBP, leading to decrease the expression of cyclin D1 and epigenetic alteration of H3K27ac and H3K18ac." (PMID 39407454, 2024). "In PF-treated hepatocellular cancer cells, HepG2 and SMMC-7721, PF mediated apoptosis by decreasing Wnt/β-catenin-related proteins, including C-myc, Cyclin-D1, and β-catenin." (PMID 38140352, 2023). "Our results demonstrated that ASS1 knockdown using siRNA promote the proliferation and invasion of Huh7, cyclin D1 was up-regulated, and bax was down-regulated, suggesting that ASS1 is a tumor suppressor gene in hepatocellular carcinoma." (PMID 38053661, 2023). "Its overexpression in hepatocellular carcinoma cell lines promotes cell proliferation and leads to increased levels of downstream ERK and cyclin D1." (PMID 35042833, 2022). "Previous studies have shown that CDK6, CCND1 and CCNE1 play an important role in the proliferation of hepatoma cells." (PMID 34980127, 2022). "In summary, CDK1, CCND1, RAF1, CDKN1B and BTRC were defined as top 5 hub target-genes, and the patients with hepatocellular cancer with high expression of CDK1 showed poor prognosis." (PMID 35836300, 2022). "It is known that targeted disruption of NLK inhibits tumor cell growth by blocking cyclin D1 and CDK2 in human hepatocellular carcinoma." (PMID 35924150, 2022). "In hepatocellular carcinoma (HCC), aberrant S100P expression suppresses cell growth and apoptosis by downregulating cyclin D1 and CDK expression at the protein level." (PMID 36187124, 2022). "The expression of STC2 also regulates the switch from G1 to S and the protein levels of cyclin D1 and pERK1/2, thus, indicating that STC2 has a direct role in the progression and metastasis of hepatocellular carcinoma." (PMID 34599150, 2021). "The silencing of EGFR by miR-302b or siEGFR led to downregulation of proliferation-related proteins, such as AKT2, CCND1, and CDK2, and resulted in the inhibition of proliferation in hepatocellular carcinoma SMMC-7721 cells." (PMID 33688369, 2021). "Other evidence for a pro-survival reprogramming of the hepatoma cells was the elevated expression of B-MYB and Cyclin D1 after SOF exposure." (PMID 32316635, 2020). "In hepatocellular carcinoma cells, HOXA10 knockdown induced cell cycle arrest at the G0/G1 phase and apoptosis by reducing the expression of Cyclin D1 and Survivin." (PMID 32296636, 2020). "Fucoidan from U. pinnatifida (commercially available or laboratory prepared) targeted p21Cip1/Waf and E2F-1 in PC-3 cells and cyclin D1 and CDK4 in mouse hepatoma Hca-F cells." (PMID 32046368, 2020). "For instance, miR-195 can bind the 3′UTRs of cyclin D1, CDK6, and E2F3, thereby suppressing cell proliferation in human hepatocellular carcinoma cells." (PMID 29426937, 2018). "In hepatocellular carcinoma (HCC) cells, suppression of FOXO1 by miR-1269 was related to dysregulation of cyclin D1 and Ki67 expression, suggesting a critical role in the growth of HCC cells." (PMID 30360388, 2018).
hepatocellular carcinoma (continued). "Recent findings demonstrated that endogenous expression of CCRK protein in hepatoma cells activates β-catenin/TCF signaling and in turn prompts the expression of downstream targets, such as CCND1 and EGFR44–46." (PMID 29497076, 2018). "Inhibition of TYRO3 in the HEP3B hepatocellular carcinoma cell line using siRNA also reduced phosphorylation of ERK1/2 and decreased cyclin D1 levels." (PMID 30501104, 2018). "Similar findings were obtained in HCC: metformin suppresses hepatocellular carcinoma cell growth through induction of cell cycle G1/G0 phase arrest, p21CIP and p27KIP expression, and downregulation of cyclin D1 in vitro and in vivo." (PMID 27577068, 2016). "In this study, we, for the first time, found that NS4B and HCV induced the expression of four cancer-related NF-κB target genes, C-myc, Mcl-1, Cyclin D1 and MMP-9 by the EOR-Ca2+-ROS-NF-κB pathway in both human hepatoma cells and primary human hepatocytes." (PMID 25875501, 2015). "In hepatocellular carcinoma cells, Oct3/4 was shown to upregulate BIRC5 (survivin) and CCND1 expression by increasing their promoter activity, thereby promoting cell proliferation and resisting cell apoptosis." (PMID 26483189, 2015). "It has also been reported that targeted disruption of NLK inhibits tumor cell growth by simultaneous suppression of cyclin D1 and CDK2 in human hepatocellular carcinoma, which implies the anti-tumor activity of miR-101." (PMID 25337143, 2014). "Other studies showed in hepatocellular carcinoma cell lines that PTK787 treatment alone reduced AKT-phosphorylation, Cyclin D1 and anti-apoptotic Bcl-2 protein expression, which correlated with cell cycle retardation/arrest and reduced cell growth." (PMID 25340839, 2014). "By manipulating OCT4 and BIRC5 expression in hepatocellular carcinoma (HCC) cell lines, the regulatory mechanism of OCT4 on BIRC5 and CCND1 were investigated." (PMID 23433354, 2013). "Our finding shows that miR-520b is able to inhibit the growth of hepatoma cells by targeting MEKK2 and cyclin D1 in vitro and in vivo." (PMID 22319632, 2012). "In contrast, GSK-3β did not correlate with Cyclin D1 expression in hepatocellular carcinoma cells and fibroblasts." (PMID 39241034, 2024). "CENPA could also activate downstream CCND1 and NRP2 by binding with the transcription factor YY1, thereby affecting the proliferation and invasion of hepatocellular carcinoma." (PMID 39620895, 2024). "Additionally, ZJP aqueous extract exhibited its prominent therapeutic effects on hepatocellular carcinoma (HCC) mainly via the regulation of cell proliferation and survival though the EGFR/MAPK, PI3K/NF-κB, and CCND1 signaling pathways." (PMID 36790599, 2023). "Similarly, Cyclin D1 (CCND1) silencing reduced CD133, Becin-1, and LC3II expression in xenograft models of cancers, and inhibition of autophagy was found to suppress hepatocellular carcinoma stem cell differentiation." (PMID 37422448, 2023). "After ASS1 knockdown using small interfering RNA (siRNA), the proliferation and invasion of Huh7 were enhanced, cyclin D1 was up-regulated, and anti-apoptotic protein bax was down-regulated, suggesting that ASS1 is a tumor suppressor gene in hepatocellular carcinoma." (PMID 38053661, 2023).
hepatocellular carcinoma (continued). "In hepatocellular carcinoma cell lines, c-Met enhanced FAK activation in a FAK kinase-dependent manner and coinduced the activation of the AKT/ERK/cyclin D1 signaling pathway, thereby upregulating cyclin D1 expression and inducing tumor cell proliferation." (PMID 35242498, 2022). "CDK1 and CCND1 are the key enzymatic complex required for mitosis, and normally activated to regulate the cell cycle of hepatocellular carcinoma cell adhesion." (PMID 35836300, 2022). "In EpCAM+ hepatocellular carcinoma (HCC), as well as advanced cirrhosis liver tissues, autocrine Wnt signaling was activated, as evidenced by elevated expression of Wnt3, β-catenin, c-Myc and CCND1." (PMID 36369033, 2022). "The current body of evidence indicates that berberine can promote the cell cycle arrest of human hepatoma HEPG2 cells in the G1 phase through the upregulation of BTG2 and the downregulation of cyclin D1, consequently inhibiting the proliferation of hepatoma cells and inducing apoptosis." (PMID 30837865, 2019). "The results showed that cyclin D1 protein expression was reduced after knockdown of DARS2 compared with expression in the negative control group, which indicated that DARS2 accelerated cell cycle progression in hepatoma cells." (PMID 29052520, 2017). "In contrast to cyclin E1, the expression of cyclin D1 was not significantly changed in both hepatoma cell lines." (PMID 28720813, 2017). "Hepatoma cells (SK-Hep1 and Huh 7) transfected with ISX shRNAi showed significant downregulation of E2F1 and DP1 protein expression as well as of proliferation markers (cyclin D1, c-Myc, Cdc25A, and PCNA) and anti-apoptotic genes (p65 and Mcl-1)." (PMID 27175585, 2016). "Moreover, in human hepatoma cell line Huh-7, it has been also shown that Ca2+ entry involving TRPC6, together with STIM1 and Orai1, increases cyclin D1 expression." (PMID 24058448, 2013). "Thus, we conclude that miR-520b inhibits the growth of hepatoma cells through targeting MEKK2 and cyclin D1." (PMID 22319632, 2012). "Of note, opposing effects of ATF3 on cyclin D1 expression have been previously documented: ATF3 binds to AP-1 motif and activates cyclin D1 in mitogen-stimulated mouse hepatoma cells, whereas it binds to ATF/CRE site and represses cyclin D1 in mouse fibroblasts stimulated by serum." (PMID 22046379, 2011). "Additionally, core protein increases and stabilizes β-catenin levels in hepatoma cell line Huh7 through inactivation of GSK-3β, which contributes to the up-regulation of downstream target genes, such as c-Myc, cyclin D1, WISP2 and CTGF." (PMID 22110662, 2011). "We assessed the expression of PPARα mRNA in human hepatocellular carcinoma tissue and non-cancerous tissue, as well as the expression of target genes of PPARα, carnitine palmitoyltransferase 1A and cyclin D1 mRNAs." (PMID 22168458, 2011). "There was a dramatic increase in the expression level of c-Myc and cyclin D1 (data not shown) after co-expression of Wnt3A and core in hepatoma cells." (PMID 22110662, 2011). "In hepatocellular carcinoma (HCC), A-to-I RNA editing of AZIN1 promotes tumorigenesis by stabilizing pro-proliferative proteins like ODC and cyclin D1, which bind more strongly to antizyme." (PMID 41361128, 2025). "Similarly, in hepatocellular carcinoma (HCC), p300 has been implicated in the significant reprogramming of super‐enhancers, leading to the upregulation of critical oncogenes, including MYC, MYCN, and CCND1, and fostering cancer cell proliferation both in vitro and in vivo." (PMID 38374872, 2024). "Importantly, in addition to its role in normal cell cycle progression, cyclin D1 is one of the most commonly overexpressed genes in human malignancies including hepatocellular carcinoma (HCC), and thus understanding its metabolic effects may provide insight into novel approaches to cancer therapy." (PMID 38152849, 2023).
hepatocellular carcinoma (continued). "Furthermore, AP-2α viability-suppressing properties were described in hepatocellular carcinoma in case of which cancer cells survival was suppressed via inhibition of Extracellular-signal-Regulated Kinase (ERK), c-Myc and CyclinD1 (CCND1) in Ras-Raf-MEK-ERK pathway." (PMID 33718178, 2021). "In hepatocellular carcinoma (HCC), UBE2M can stabilize β-catenin and increase the level of its downstream protein cyclin D1 to promote the progression from G0/G1 phase to S phase." (PMID 33827629, 2021). "In addition, restoring ARID2 expression in hepatoma cells suppressed cell growth and tumor progression in mice while ARID2 inhibition resulted in upregulation of cell cycle proteins such as cyclin D1 and cyclin E1, suggesting a tumor suppressive role for ARID2 in HCC." (PMID 31056726, 2019). "For example, inhibition of FGF19 in CCND1-amplified tumors (11q13 amplification) using anti-FGF19 antibodies has been shown to be an effective therapy for hepatocellular carcinoma (HCC), and the blockage of its FGFR receptors has shown promising clinical results in FGF19/FGF4+ HCC." (PMID 36980521, 2023).